KLF4 (KLF transcription factor 4)
Diseases named in the same sentence as KLF4 in open-access papers (continued):
Sharing a sentence is not in itself a finding about the gene and the disease.
cancer (continued). "Notably, KLF-4 stands out as the KLF with the highest number of interactions, likely because of its well-established roles in pluripotency, cancer, and, most importantly, cardiovascular development and disease." (PMID 38672763, 2024). "It modulates cancer stem cell stemness and pluripotency by targeting many embryonic transcriptional factors that enhance the oncogenic activity of metastatic cancers, including OCT4, SOX2, NanoG, and KLF4." (PMID 37513415, 2023). "In addition, VEGFA and B, their receptors KDR and FLT1, and downstream TFs, including KLF4 and ETS1, were found in this analysis as targets of cooperative ENHs, in line with the pivotal role of angiogenesis in promoting cancer metastatic spreading." (PMID 37408506, 2023). "The expression levels of Nanog, c-Myc and KLF4 in cancer tissues were significantly higher than those in adjacent non-cancer tissues in our forty pairs of HCC tissues." (PMID 36902429, 2023). "They activate cancer cell signaling pathways and transcription factors, including IGF1/α6β4 complex, FGFR2, TIMP, DNA replication and mTOR signaling, Smad7, KLF4, and TBX2, and downstream proto-oncogenes such as MYC, MET, and CDK1, which facilitate cancer progression." (PMID 37046676, 2023). "Silencing of miR-218-5p inhibited activation of the JAK2/STAT3 pathway by targeting KLF9, while KLF4, which belongs to the same family, could inhibit the JAK2/STAT3 pathway, which in turn affects cancer cell development." (PMID 37465460, 2023). "Moreover, the overexpression of KLF4, SOX2, and NANOG were found in several malignancies, and their expression levels were correlated with poor prognosis, advanced-stage cancer, and shorter patient survival." (PMID 36553636, 2022). "We performed qRT-PCR to analyzed the expression of cancer stemness markers and found that the overexpression of miR-200b in the MCF-7/shDicer cells reduced the expression of the stemness markers Oct-4, Nanog, SOX-2, and KLF4." (PMID 35951366, 2022). "Despite the participation of KLF4 in the differentiation of the keratinocyte, it can also upregulate the transcription of many genes, indispensable for EMT and cell growth, so it also serves as an oncogene in many cancers." (PMID 35327461, 2022). "In the ethnicity subgroup analyses, the results showed that KLF4 expression had no impact on OS (HR = 0.77, 95% CI: 0.56–1.05, P = 0.1) in Asian cancer patients or OS in non-Asian patients (HR = 1.44, 95% CI: 0.82–2.53, P = 0.2)." (PMID 35177016, 2022). "In the hypercholesterolemic urinary bladder cancer (UBC) mouse model, ezetimibe significantly suppress HFHC-induced serum lipid (TC, LDL-C, and ox-LDL), and decrease the percentage of cancer cells (CK5+, CK14+, and p-STAT3+) and cancer stemness markers (ALDH1A1, CD44, KLF4, and Nanog)." (PMID 35924044, 2022). "Similarly, the decreased levels of SOX4, SOX9, Nanog,CD44, KLF4 and ABCG2 were observed from the harvested KYSE450 tumors related to miR-637 overexpression, indicating the inhibition of cancer cell stemness by miR-637." (PMID 36329557, 2022). "Similarly, lncRNA CCAT2 promoted expression of Oct4, nanog, and KLF4 genes (Kruppel-like factor 4) and growth of ALDH+ cancer stem cells in TNBC via targeting miR-205." (PMID 36685962, 2022). "In addition, if p38 was inhibited, resistant HNSCC cells showed a higher DNA damage response and exhibited a decreased expression of cancer stem-cell markers such as CD44 and KLF4." (PMID 36289744, 2022). "KLF4 is able to induce pluripotent stem cells and HIF-1α reportedly induces its expression in cancer cells, suggesting that hypoperfusion might be involved in KLF4 expression in the AAA wall." (PMID 33672844, 2021). "In this heterogeneous area the TGF-β1-responding cells are located in the outer ring of the cancer cell nest, and are labelled with Slug antibody, whereas, non-responding cells in the central part of the cancer cell nest are Slug-negative and contain KLF4." (PMID 33802627, 2021).
cancer (continued). "The transformation of fibroblasts to a pluripotent state was possible due to four transcription factors, namely octamer-binding transcription factor 3/4 (Oct-3/4), sex-determining region Y-box 2 (Sox2), Kruppel-like factor 4 (KLF4), and cancer-related Myc gene." (PMID 34873560, 2021). "During cancer progression, stemness of cancer cells is maintained by hypoxia through different mechanisms, including enhancement of EMT and the transcriptional induction of stemness related genes (Oct4, POU5F1, Sox2, Nanog, BMI1, Myc and KLF4)." (PMID 33407613, 2021). "We found a weak but significant positive correlation between KLF4 and NOXA (gene name PMAIP1) mRNA expression levels (R-score = 0.21 in cancers, R-score = 0.38 in normal tissues) using the total dataset of Gene Expression Profiling Interactive Analysis database." (PMID 33918002, 2021). "The upregulation of HIF under hypoxia microenvironment has been shown to induce the expression of known pluripotent stemness factors, such as KLF4, MYC, OCT4, SOX2, and NANOG, to reprogram towards a cancer stem cell (CSC) phenotype and to influence the expansion of CSC populations." (PMID 34798868, 2021). "This indicates that KLF4 may be upregulated by glucose starvation through AMPK, but this pathway’s regulatory effects may be altered in cancer cells." (PMID 33917010, 2021). "Expression of KLF4 and SALL1 in cancer suppression and carcinogenesis." (PMID 34195082, 2021). "However, we found that the HG-induced increased expression of KLF4 significantly decreased the expression of TERT in HUVECs, which is inconsistent with previous observations in stem cells and cancer cells." (PMID 34744738, 2021). "Another study on hepatocellular carcinoma revealed the ability of KLF4 to turn noncancer stem cells into cancer stem cells." (PMID 35008527, 2021). "Moreover, the expression levels of the cancer stemness markers, NANOG, CD44, and KLF4, were markedly higher in 3D spheroids than in 2D monolayers." (PMID 34948357, 2021). "An analysis of in vitro transcriptomic datasets and cancer patient samples from The Cancer Genome Atlas (TCGA) revealed a negative correlation between the KLF4 levels and enrichment of EMT." (PMID 34680284, 2021). "Interestingly, KLF4 and other stemness genes (Oct4, Sox2 and c‐Myc) have proposed as putative targets for HCC therapy because they contributed for maintaining cancer stem cells (CSCs), having strong chemoresistance." (PMID 34114341, 2021). "Our simulations suggest that KLF4 overexpression can promote a phenotypic shift toward a more epithelial state, an observation suggested by the negative correlation of KLF4 with EMT-TFs and with transcriptomic-based EMT scoring metrics in cancer cell lines." (PMID 34680284, 2021). "For example, cancer-derived exosomal hsa-miR-25-3p can mediate the formation of pre-metastatic niche by inducing angiogenesis and vascular permeability through silencing KLF2 and KLF4, thereby promoting CRC metastasis." (PMID 35096570, 2021). "We hereby propose KLF4 as a potential MET-inducing transcription factor (MET-TFs) based on in silico model predictions and their experimental validation across multiple in vitro and cancer patient sample datasets." (PMID 34680284, 2021). "Indeed, knockdown of USP4 in the cancer cell lines D121, LLC, H1299, and HCC827 increased expression of the stemness genes Oct4, Sox2, Nanog, KLF4, ABCG2, and ALDH1 in different degree in different cell lines as measured by RT-qPCR." (PMID 31936290, 2020). "For the cancer types that performed the worst, liver hepatocellular carcinoma included none of the used oncogenes (AR, KLF4, PDGFRA, and RET) or tumor suppressors (BRCA2, CDKN2A, and TSC1) that were linked to it." (PMID 31900418, 2020). "Increased RAP1 levels were associated with a poor survival rate, indicating that RAP1 could serve a marker for survival prediction in these types of cancer, although the precise relationship between RAP1 and KLF4 needs to be investigated further." (PMID 33266506, 2020).
cancer (continued). "CSCs drive cancer initiation, progression, metastasis, recurrence and drug resistance, and express Nanog, CD133, CD90, SOX2, EpCAM, CD44, Klf4 and Oct4, some of which may functionally support liver CSC phenotypes like invasiveness and chemoresistance." (PMID 33343368, 2020). "Compared with control xenograft tumors, the mRNA levels of cancer stemness-related genes, including ABCG2, BMI1, NANOG, KLF4, and OCT4 were increased and the protein expression of ABCG2, Oct4, Bmi-1, and CD44 were also increased in HBx-expressing xenograft tumors." (PMID 32168902, 2020). "Finally, miR-486-5p also promote the expression of five genes with promoting cancer roles: KDM4C, PPARD, KLF4, STAT3, and TCF7l2." (PMID 33227890, 2020). "Both in the familial heredity and sporadic, there is a decrease or no expression of KLF4, and the cancer progresses from the first stage to the fourth stage." (PMID 31724937, 2019). "The factors OCT4, Nanog, SOX2, Klf4, C-MYC, and Lin28 play crucial roles in cancer progression." (PMID 31921617, 2019). "Our finding of higher KLF4 and OCT4 protein expression in the stroma of HGCA may reflect the migration of cancer cells by EMT, away from the epithelium, which has been postulated as a major factor in CRC progression." (PMID 31491003, 2019). "The effect of the treatment was first evaluated by measuring the expression of stem cell transcription factors SOX2, NANOG, OCT4, SCA-1, and KLF4 for both cell cancer and non-CSC populations." (PMID 29868483, 2018). "Furthermore, ectopic expression of PRMT5 or KLF4 in MCF-7 cells leads to cellular accumulation of methylated KLF4 protein, which reduces transcription of the pro-apoptotic gene BAX, thereby promoting cancer cell growth and survival." (PMID 30613353, 2018). "OCT4, SOX2, NANOG, Krüppel-like factor 4 (KLF4) and c-MYC play a significant role in triggering pluripotency in somatic cells, and they have been used to identify CSC subpopulations within various types of cancer." (PMID 30177970, 2018). "Since CD44 positivity represent stemness of a cancer cell line along with other markers such as OCT3/4, SOX2, KLF4, and Nanog, this approach may contribute to the retardation of tumor growth by restricting cancer stem cell population." (PMID 30619758, 2018). "Although the anti-cancer agents fluorouracil and cisplatin suppressed the proliferation of miPS-LLCcm cells, these drugs did not alter the expression of stemness markers, including Nanog, SOX2, c-Myc, Oct3/4 and Klf4." (PMID 29228699, 2017). "Accordingly, embryonic stem cells and cancer cells have been reported to share a common gene expression pattern, and the expression of ESC markers (such as HMGA2, KLF4, NOTCH1, OCT3/4 and SOX9) that are known to play a key role in pluripotency, self-renewal, and cancer, is increased in many tumors." (PMID 29383160, 2017). "Further studies revealed that KLF4 was directly bound to the promoter regions of the hTERT gene, and the MAPK signaling pathway may participate in regulating cancer cell growth and hTERT expression." (PMID 27153563, 2016). "Accumulated evidence from various cancer types strongly support the hypothesis that hypoxia sustains the self-renewal characteristics of a portion of cancer cells in hypoxic niches mainly due to the upregulation of Oct4, NANOG, SOX2, Klf4, and c-myc." (PMID 26042045, 2015). "In addition, the same group recently revealed a correlation between KLF4 expression and production of the C-X-C motif chemokine CXCL5 (CXCL5) by primary cancer cells." (PMID 24429391, 2014). "Hypoxia, via HIF-1α-mediated transcription, has been shown to induce an embryonic stem cell-like transcriptional program including pluri-potency-inducing markers like OCT3/4, Nanog, c-Myc, KLF4 and SOX-2 in several cancer cell lines derived from various tissues." (PMID 23185562, 2012).
cancer (continued). "Moreover, as one of the Yamanaka factors, KLF4 is deeply connected with the CSC niche and could act as the seed for the proliferation and metastasis of cancer cells." (PMID 41532367, 2026). "In the driver gene set, i.e., genes responsible for cancer development and progression, the only downregulated gene was KLF4, which however does not reach statistical significance, and all target genes with statistically significant differences were upregulated." (PMID 39980141, 2025). "As cancer cells have higher levels of ROS with generally more oxidizing environments there would be more protein disulfides present to act as covalent traps for intracellular ORP100S but not TRX, limiting the amount of reduced ORP100S available to interact with KLF4." (PMID 40932638, 2025). "Furthermore, transcription factors such as Nanog, OCT4, SOX2, and KLF4, which are critical for maintaining stem cell pluripotency, have been found to interact with EMT regulators to enhance the stem-like characteristics of cancer cells." (PMID 39403386, 2024). "Under the paradoxical joint action of the two molecules, whether cancer cell proliferation is inhibited or promoted may depend on the expression level of E-cadherin, a factor with an essential role in EMT and regulated by both KLF4 and TGF-β1." (PMID 36761967, 2023). "Notably, SOX2, OCT4, KLF4, and the pluripotency reprogramming facilitator c-MYC, known for their role in establishing and maintaining stem cell pluripotency, are also aberrantly expressed in certain cancer cells." (PMID 37760529, 2023). "Targeting MEX3A or KLF4 not only suppressed CRC cell proliferation, but also increased their differentiation status, suggesting that it might represent a new potent target for cancer differentiation therapy upon CRC." (PMID 36276637, 2022). "SATB2 may be a driving force for developing cancer stem‐like phenotypes in damaged hepatocytes where induction of stem cell markers (CD44, CD90, EpCAM, AFP and LGR5) and pluripotency maintaining factors (POU5F1/Oct4, Sox‐2, Nanog and KLF4) was prominent." (PMID 35152538, 2022). "More importantly, we observed for the first time that KLF4-mediated xCT upregulation served as negative feedback during ferroptosis progression, which might contribute to drug resistance in cancer treatment." (PMID 34040532, 2021). "Dysregulation of KLF4′s cell death pathway could lead to more evasive cancers that are no longer killed following glucose starvation." (PMID 33917010, 2021). "Moreover, USP11 and KLF4 levels were found to be negatively correlated in HCC cells and to have the opposite prognostic trend regarding HCC in the clinical setting, which supports the essential role of USP11 in cancer development." (PMID 34114341, 2021). "In addition, the downregulation of SPN also induces an increase in the stemness properties of the cells, such as the expression of some cancer stem cell markers (NANOG, OCT4, SOX2, and KLF4) and enrichment in CD44+/CD24- cells, cancer-initiating cells in breast tumors with stem cell properties." (PMID 34066428, 2021). "Additionally, future studies remain necessary to investigate KLF4′s role in non-Warburg cancer metabolism, such as metabolic shuttling and lipid metabolism." (PMID 33917010, 2021). "More importantly, we observed for the first time that KLF4-mediated xCT upregulation serves as negative feedback during ferroptosis progression, which might contribute to drug resistance in cancer treatment." (PMID 34040532, 2021). "g., transfection) of stemness genes, such as OCT3, SOX2, KLF4, MYC, NOTCH1, NANOG, and LIN28, as well as epithelial-mesenchymal transition (EMT) genes (ZEB1, SNAI, VIM, TWIST, etc.), leads to stem phenotype induction and increased stem-like cancer cell activity." (PMID 32523653, 2020).
cancer (continued). "Hypoxia signalling can induce HIF-dependent expression of known pluripotent factors, such as KLF4, MYC, OCT4, SOX2, and NANOG, which have an important role in the dedifferentiation process under hypoxic conditions, inducing cancer stemness and repressing cancer cell differentiation." (PMID 33339101, 2020). "To search for drugs that could suppress KLF4 as a potential therapeutic strategy, we have conducted a nonbiased screening of an anti‐cancer compound." (PMID 33231937, 2020). "Because the introduction of SOX2, OCT4, MYC, and KLF4 is sufficient to reprogram differentiated cells into iPSC with ESC properties, the combined expression of these factors has been hypothesized to initiate tumors and promote cancer progression." (PMID 32427884, 2020). "Consistent with previous studies indicated, KLF4 inhibited the growth of many cancer cell lines, including LC cells, and we further revealed that exogenous PLAC8 protects H1299 cells from KLF4-induced apoptosis and rescues the inhibitory effect of KLF4 on cell proliferation." (PMID 29789534, 2018). "Overexpression of miR-103 has been found in several type human cancers and previous studies reported that miR-103 could enhance the proliferation, migration, and invasion of cancer cells by targeting anti-oncogenes DICER and PTEN, TIMP-3, PDCD10, KLF4 respectively." (PMID 28445396, 2017). "Moreover, Klf4 plays a critical role in reprogramming non-tumorigenic human mammary epithelial cells into cancer stem cells by defined reprogramming factors." (PMID 29212199, 2017). "We also observed that A2780 cells treated with exosomes from platinum-resistant cells displayed a 2- to 5-fold (P<0.05) decrease in KLF4, a transcription factor that regulates genes essential to EMT including E-cadherin and vimentin and has been shown to regulate EMT in multiple types of cancers." (PMID 28060758, 2017). "However, the dependability of KLF4 serving as a prognostic biomarker has not been coming to an agreement in different cancers for the insignificant even opposite results." (PMID 29062163, 2017). "The expression of Oct4, Nanog, Myc, Sox2, and Klf4 in the current study correlated well with data reported in the HPA which reveals expression of Oct4 in 88 % of cancers, Sox2 in 88 % of cancers, Myc in 78 % of cancers, Klf4 in 28 % of cancers, and Nanog in 7 % of cancers." (PMID 26412983, 2015). "The biological effects of KLF4 seem to depend on cancer type rather than unique." (PMID 21978458, 2011). "Thus, the reports point towards an alternative pathway by the dietary phytochemicals to increase E-cadherin expression in cancer cells which may not necessarily involve KLF4 mediation." (PMID 29899271, 2018). "Notably, the suppression of their common target KLF4 could inhibit the expression of various Erk5 (mitogen-activated protein kinase 7) targets and further affect the MAPK cascade in the regulation of endothelial integrity in cancer." (PMID 26692821, 2015). "In addition, expression of Kruppel-like factor 4 (KLF4), Ras guanyl nucleotide exchange factor 1A (RASGEF1A), and polo-like kinase 2 (PLK2) have been reported to exhibit anti-apoptotic and growth-promoting activity in human cancer cells and are also up-regulated by RASSF1C over-expression." (PMID 22591718, 2012). "Moreover, we demonstrated that loss of BMI-1 in EC cells reduces expression of stemness gene SOX-2, KLF4 and drug-resistance gene MRP-1, suggesting that BMI-1 expression maybe required for the proliferation of cancer cells, as well as for regulation of stemness properties of EC cells." (PMID 21851624, 2011). "Compatible to our results, the authors identified a negative correlation of KLF4 with EMT-related TFs and with transcriptomic based EMT scoring metrics in the Cancer Cell Line Encyclopedia (CCLE) cell lines." (PMID 35219646, 2022). "More consistent with a pro-oncogenic role of KLF4 in AML, DNA methylation did not appear to play a significant role in AML cell lines, in contrast to other cancer types." (PMID 33659038, 2021).